UCP2 (uncoupling protein 2)
Diseases named in the same sentence as UCP2 in open-access papers (continued):
Sharing a sentence is not in itself a finding about the gene and the disease.
cancer (124 papers, 2002 to 2025). A tumor composed of atypical neoplastic, often pleomorphic cells that invade other tissues. "This study revealed that elevated UCP2 expression was associated with improved prognosis in cancers such as BLCA and CESC, whereas it correlated with poorer outcomes in LGG, MESO, and UVM." (PMID 41403699, 2025). "Uncoupling proteins are known to interfere with ATP production by inducing proton leak, UCP2 in particular has been reported to be expressed in aggressive cancers and has been implicated in promoting chemoresistance." (PMID 39965288, 2025). "For example, elevated UCP2 expression has been associated with enhanced cell proliferation and resistance to apoptosis in cancer." (PMID 41614832, 2025). "In line with this conclusion, we have recently showed that in KRAS-mutated PDAC cancer cell lines, UCP2 expression decreases ROS levels by exporting aspartate out of mitochondria." (PMID 36672360, 2023). "In line with this notion, UCP2 overexpression has been reported in several cancers and is associated with chemoresistance." (PMID 36672360, 2023). "The discovery that drug-resistant tumor cells express high levels of UCP2, which has been linked to protection against oxidative stress, pointed to UCP2 as a new drug target for cancer treatment." (PMID 37175829, 2023). "Among them, UCP1 and UCP2 are associated with multiple malignant tumors, including colon cancer, non-small cell lung cancer, pancreatic cancer, and BC." (PMID 35874806, 2022). "UCP2 expression is associated with cancer and modulates energy metabolism in response to elevated ROS levels." (PMID 33924958, 2021). "Although this suggests that the UCP2 A allele has anti-cancer properties; literature data point to different results." (PMID 34481515, 2021). "Numerous resistant cancer cell lines display higher UCP2 expression, which has been associated with reduced ROS production, an altered mitochondrial membrane potential and protection against cytotoxicity-mediated apoptosis." (PMID 35582026, 2021). "By means of TWAS, we recovered seven genes (APOC1, APOE, BIN1, HMGB1, PRKAA1, SQSTM1, and UCP2) significantly associated to AD traits and some cancer models." (PMID 31608105, 2019). "Some reports have indicated that UCP2 acts as a tumor suppressor because it has been associated with decreased proliferation and malignant progression in cancer cells." (PMID 29254145, 2017). "Inhibition of UCP2 in cancer cells have been shown to increase susceptibility of drug-resistant cancer cells to cytotoxic agents, indicating UCP2 is overexpressed in these cancers." (PMID 27129291, 2016). "We conclude that UCP2 over-expression is a general phenomenon linked to the Warburg Effect in cancer." (PMID 21935467, 2011). "Our proposal starts with the assumption that UCP2 over-expression is an adaptive response which limits ROS in cancer lines by causing uncoupling." (PMID 19480693, 2009). "An increase in UCP2 has been reported to be associated with reduction of respiratory ATP production in several cancer lines that have preserved TCA cycle enzymes." (PMID 19480693, 2009). "Increasing data has indicated that UCP2 is associated with energy metabolism regulation in cancers." (PMID 38217303, 2024). "In addition, an increasing number of reports have implicated UCP2 in the metabolic adaptations of cancer cells, known as the so-called Warburg effect." (PMID 37175829, 2023). "These latter studies showed that, at 10 mM acetoacetate, cancer cell proliferation was significantly reduced, with associated decreases in ATP production and, concomitantly, over-expression of uncoupling protein-2 (UCP-2), while untransformed cells were unaffected by this agent." (PMID 37760956, 2023).
cancer (continued). "However, when cells are damaged in metabolic diseases, infections or cancers, a loss of UCP2 will have more drastic consequences." (PMID 36499405, 2022). "The most commonly supported theory about the role of UCP2 in cancer cell proliferation and chemoresistance has been linked to its ability to reduce ROS levels by lowering the electrochemical gradient across the IMM thanks to its possible protonophoric activity." (PMID 35008407, 2022). "Indeed, through the physiological regulation of ROS, the modulation of metabolism and the control of the immune system, UCP2 has been implicated in the control of autoimmune diseases, cardiovascular dysfunction, neuronal pathologies and cancers." (PMID 36499405, 2022). "In cancer cells, UCP2 may play a role in causing apoptosis 15, 16, while several UCP2 functions remain unclear." (PMID 33859525, 2021). "Notably, combined overexpression of Rab32, a protein kinase A-anchoring protein fostering the ER-mitochondrial tethering, and UCP2 caused a significant drop in cancer cells' viability." (PMID 33614647, 2021). "UCP2 could play a key role in many biological pathways including cell metabolism and proliferation, thus contributing to cancer growth and drug resistance; moreover, polymorphisms of its gene were associated with diabetes and obesity in humans." (PMID 32842667, 2020). "Therefore, a combined upregulation of PRMT1 and UCP2 as crucial risk in various cancer types, as found in our TCGA analysis, seems to be reasonable." (PMID 29113301, 2017). "Since the alterations in cellular metabolism and the metabolic switch are relevant to many tumor cells, we believe that PFKFB2 could potentially be an interesting candidate in the association of tumorigenesis and metabolism in UCP2 highly expressed cancers." (PMID 29221144, 2017). "Furthermore, GNP inhibits drug resistance in cancer cells by increasing the susceptibility to oxidative stress and cytotoxic agents, and all of these effects are related to its high affinity for uncoupling protein-2 (UCP2)." (PMID 26771380, 2016). "There is increasing evidence that UCP2 expression patterns are linked to cancer and may further modulate energy metabolism in response to high ROS levels." (PMID 21712825, 2011). "Inhibition of UCP2, by enhancing ROS production, may increase susceptibility of cancer cells to apoptosis." (PMID 24281083, 2010). "However, in more types of cancer, UCP2 is associated with immune-related pathways." (PMID 41403699, 2025). "The aim of the current study was to test the hypothesis that genipin, an extract from Gardenia jasminoides which has been shown to inhibit UCP2 and improve insulin secretion, can inhibit UCP2 in the drug resistant MX2 cancer cells to increase oxidative stress and susceptibility to cytotoxic agents." (PMID 20967268, 2010). "UCP2 was primarily cytoplasmic in most samples, although nuclear expression was observed in some invasive cancer cells." (PMID 41367865, 2025). "While UCP1, UCP3, SLC25A27, and SLC25A14 were frequently downregulated in most cancers, UCP2 showed consistent upregulation, indicating divergent functional roles in oncogenesis." (PMID 41403699, 2025). "STAT1 (Signal Transducer and Activator of Transcription 1) and UCP2 (Uncoupling Protein 2), known for their roles in other cancers, were selected for further validation." (PMID 41367865, 2025). "The compelling evidence that both exogenous mitochondrial uncouplers and UCP1 activation in BAT impair tumor growth presents a paradox when compared with the frequent upregulation of endogenous UCPs—particularly UCP2—in human cancers." (PMID 40983641, 2025).
cancer (continued). "Previous studies indicate that UCP2 plays context-dependent roles in tumorigenesis across multiple cancer types, acting as either an oncogene or a tumor suppressor." (PMID 41403699, 2025). "For these reasons, the inhibition of UCP2 under pathological conditions such as cancer is highly important." (PMID 40362341, 2025). "DNA methylation analysis revealed a general inverse correlation with mRNA expression levels of UCP genes, a trend particularly pronounced for UCP2 in the pan-cancer context." (PMID 41403699, 2025). "Coculture experiments with adipocytes showed that FABP4 and UCP2 promote lipid metabolic reprogramming, facilitating cancer cell survival in a dormant state." (PMID 39823981, 2025). "As mentioned in the introduction, UCP2 is aberrantly expressed under various pathological conditions, including metabolic disorders, cancer, and inflammatory diseases." (PMID 41300438, 2025). "We observed a significant increase in UCP2 expression in both epithelial and stromal areas as lesions progressed to cancer." (PMID 41367865, 2025). "In conclusion, our results showed that STAT1 and UCP2 are upregulated in cervical precursor lesions as they progress to cancer." (PMID 41367865, 2025). "Given the pivotal role of macrophages and their activation and polarization in various pathophysiological contexts, ranging from cancer to infection, inflammatory responses, and tissue repair, we aimed to efficiently modulate UCP2 activity in macrophages." (PMID 41300438, 2025). "Our findings indicate that UCP2 is often overexpressed in various cancer types, correlating with poor prognosis and aggressive tumor characteristics." (PMID 41403699, 2025). "A comprehensive understanding of UCP2 role within the broader context of cancer metabolism will help by the development of targeted therapies capable of disrupting the metabolic flexibility essential for cancer cell survival." (PMID 38986826, 2024). "In cancer, UCP2 is upregulated in various malignancies, including cancers of the breast, colon, gallbladder, head and neck, skin, prostate, pancreas, cervix, lung, and HCC as well as in leukemia." (PMID 39795950, 2024). "Certain investigations have also demonstrated that overexpression of the antioxidant UCP2 in cancer cell lines promotes aerobic glycolysis, tumor proliferation, and resistance to apoptosis-induced chemotherapy." (PMID 38255314, 2024). "Studies with thouroughly evaluated antibodies have demonstrated the high abundance of UCP2 in pluripotent stem cells, immune cells and cancer cells." (PMID 38986826, 2024). "Using a wide range of cancer cell types from both mice and humans, we show that although UCP2 is expressed in all cancer cells, the abundance of UCP2 varies between different cancers." (PMID 38986826, 2024). "Mitochondrial uncoupling protein 2 (UCP2) has attracted interest because of its abundance in rapidly proliferating cells, including cancer cells, and its involvement in cellular metabolism." (PMID 38986826, 2024). "In conclusion, our findings demonstrate that UCP2 plays a more complex, context-dependent role in cancer cell metabolism and survival." (PMID 38986826, 2024). "Currently, the therapeutic strategy of using UCP2 to regulate metabolic reprogramming in tumors has been confirmed in cancer research." (PMID 38429403, 2024). "UCP2 plays a vital role in cancer aggressiveness and drug resistance from its capacity to suppress ROS production and inhibit cell apoptosis." (PMID 38217303, 2024). "Uncoupling protein 2 (UCP2) has been found upregulated in various cancer types, leading to tumorigenesis, cancer progression and chemotherapy resistance." (PMID 38217303, 2024). "Through metabolic and energetic transformation, oxidative stress and reactive oxygen species (ROS) can be decreased by metabolic and energetic transformation, and overexpression of UCP2 in cancer cells to avoid cell apoptosis." (PMID 38217303, 2024).
cancer (continued). "UCP2 abundance was also differentially affected by nutrient availability in different cancer cells, but UCP2 was generally down-regulated under hypoxia." (PMID 38986826, 2024). "Our investigation of UCP2 expression in various human and mouse cancer cell lines aimed to elucidate its links to metabolic states, proliferation, and adaptation to environmental stresses such as hypoxia and nutrient deprivation." (PMID 38986826, 2024). "Uncoupling protein 2 (UCP2) plays a pivotal part in the malignancy of cancer and its capacity to develop resistance to pharmaceutical interventions." (PMID 38217303, 2024). "Another study showed that UCP-2 expression in cancer cells determined the immunomodulatory function of the tumor microenvironment (TME) and had a direct effect on the survival of cancer cells." (PMID 36900198, 2023). "Treatment with genipin, a UCP-2 inhibitor, significantly increased the antitumor effect of trastuzumab and increased the apoptosis of cancer cells." (PMID 36900198, 2023). "Traditionally, the tumour-promoting effect of UCP2 has been ascribed to a reduction in ROS levels in cancer cells, achieved by lowering the electrochemical gradient across the inner mitochondrial membrane due to its protonophoric activity." (PMID 36672360, 2023). "UCP2 is often highly expressed in cancer cells that are resistant to drugs to inhibit ROS accumulation and apoptosis." (PMID 37744277, 2023). "Another research group demonstrated that gemcitabine-induced UCP-2 mRNA expression, which in turn resists gemcitabine-induced damage to cancer cells, elucidates UCP-2-induced resistance." (PMID 36900198, 2023). "This cataplerotic function of UCP2 is of crucial importance in cancer metabolism because many cancers are known to rewire their metabolism towards enhanced glutamine utilization or “glutamine addiction”." (PMID 36672360, 2023). "UCP2 was significantly up-regulated in 11 cancers including BC and significantly down-regulated in 6 tumor types." (PMID 35874806, 2022). "Nevertheless, based on all the studies cited above, the inhibition or activation of UCP2 according to the metabolic status of the tumor represents a therapeutic opportunity to improve cancer remission." (PMID 36499405, 2022). "Our data did not reveal changes in the expression of UCP1, a marker of WAT browning involved in the thermogenic waste of energy during cancer cachexia, whereas UCP2 levels were reverted by MitoQ treatment." (PMID 35392166, 2022). "We first analyzed the expression of UCP1 and UCP2 between normal and tumor samples from 34 cancer specimens in TCGA." (PMID 35874806, 2022). "UCP2 is therefore considered today in many studies based on the Oncomine database as a potential cancer biomarker." (PMID 36499405, 2022). "Tumor-suppressing role of UCP2 is supported by facts that forced UCP2 expression attenuates cell proliferation in vitro in both mouse and human cancer cell lines." (PMID 35090503, 2022). "Especially cancer cells show a clear increase in UCP2 but also PRMT1 expression and both proteins when highly expressed are prognostic markers for lung carcinoma patients." (PMID 35778442, 2022). "Overall, the role of UCP2 on metabolism, oxidative stress and cell division rate defines this protein as a relevant target for cancer treatments." (PMID 36275699, 2022). "Through the roles of UCP2, studies have characterized the involvement of UCP2 in the regulation of tumor cell sensitivity to cancer therapies." (PMID 36499405, 2022). "Overall, these studies showed that regulating UCP2 expression, either positively or negatively depending on the type of cancer, represents a therapeutic strategy to be considered to improve responses to chemotherapy." (PMID 36499405, 2022). "In brief, genipin inhibits UCP2 to attenuate generation of reactive oxygen species (ROS), leading to ROS/c-Jun N-terminal kinase-dependent apoptosis of cancer cells." (PMID 35628447, 2022).
cancer (continued). "Most data published on the role of UCP2 in cancer comes from experiments carried out in cancer cell lines." (PMID 35008407, 2022). "Although all these results indicate that UCP2 is involved in the glycolytic metabolism of cancer cells, some data are contradictory." (PMID 36499405, 2022). "The role of UCP2 in cancer cell metabolism and chemoresistance has been demonstrated in many different cancer types." (PMID 35008407, 2022). "Since the maintenance/progression of many tumors relies on glutamine utilization, the cataplerotic function of UCP2 is essential to cancer cells using glutamine as carbon and reduced nitrogen source for biosynthetic processes and redox homeostasis." (PMID 35008407, 2022). "Under the condition of MICU1 methylation by PRMT1 in aging or cancer, UCP2 that binds to methylated MICU1 destabilizes CJ, disrupts SMPGs, and facilitates fast Ca2+ uptake via the CM." (PMID 35778442, 2022). "After the study was published, genipin has been used as a tool for studying UCP2 biology with numerous studies using genipin to inhibit UCP2 in cancer cells." (PMID 35628447, 2022). "In summary, UCP2 over-expression, which appears as a mechanism to protect cancer cells from excessive ROS production, is considered a target of cancer therapy without affecting normal cells." (PMID 35628447, 2022). "Among the metabolic actors, the mitochondrial transporter uncoupling protein 2 (UCP2), whose expression is increased in many cancers, has been identified as an interesting target in tumor metabolic reprogramming." (PMID 36499405, 2022). "After the treatment of gallbladder cancer cells (G-415) with gentamicin, these transcription factors were activated and, in combination with UCP2, promoted cancer cell survival during chemotherapy." (PMID 36499405, 2022). "Nevertheless, we believe that the metabolic adaptations enabled by UCP2 are more pronounced in a stressful context, such as cancer." (PMID 36499405, 2022). "To investigate potential regulatory mechanisms of the mitochondrial Ca2+ uptake routes in cancer cells, we modulated mitochondria–ER tethering and the expression of UCP2 and analyzed mitochondrial Ca2+ homeostasis under the various conditions." (PMID 33614647, 2021). "Under conditions of elevated protein methyltransferase 1 (PRMT1), as the case in cancer or aging, UCP2 interacts with PRMT1-methylated MICU1 and re-establishes its Ca2+ sensitivity resulting in a normalization of mitochondrial Ca2+ uptake." (PMID 33614647, 2021). "In this study, a plasmid containing the promoter region of UCP2 was constructed, transfected into three cancer cell lines, and the activity of the UCP2 promoter was measured." (PMID 33859525, 2021). "Nonetheless, some studies have reported that UCP2 expression confers a pro-survival advantage for cancer cells." (PMID 33935708, 2021). "The results of the present study showed that the UCP2 promoter region in Hep3B cells has numerous methylated sites compared with other cancer cells and that UCP2 expression is inhibited by methylation." (PMID 33859525, 2021). "In the present study, the transcriptional difference of UCP2 mRNA among the three cancer cell lines was identified." (PMID 33859525, 2021). "Particularly SeMet increases the redox status of cancer cells by increasing the expression of uncoupling protein 2 (UCP2) and redox enzymes and also reducing oxidative damage to proteins and lipids." (PMID 33935708, 2021). "In summary, we found a tendency to an inverse correlation of UCP2 and proteins stabilizing mitochondrial-ER interaction in all three investigated cancer types." (PMID 33614647, 2021). "ER-mitochondrial linkage was found to support a mitochondrial Ca2+ uptake route dependent on uncoupling protein 2 (UCP2) in cancer cells." (PMID 33614647, 2021). "UCP-2 is widely expressed in cancer cells and can alleviate oxidative stress by suppressing mitochondrial production of reactive oxygen species (ROS)." (PMID 34481515, 2021).